NUDT21 (nudix hydrolase 21)
Diseases named in the same sentence as NUDT21 in open-access papers (continued):
Sharing a sentence is not in itself a finding about the gene and the disease.
kidney damage (1 paper, 2021). "The other six markers, CDC5L, HNRNPU, NUDT21, PAPOLA, POLR2B, and WBP4, were all negatively correlated with GFR, indicating that these genes may aggravate kidney damage in patients with LN." (PMID 34557492, 2021).
lung adenocarcinoma (1 paper, 2021). A carcinoma that arises from the lung and is characterized by the presence of malignant glandular epithelial cells. "Down-regulation of CPSF5/CFIm25/NUDT21 was seen to promote shortening of the 3′UTRs of IGF1R, CCND1 and GSK3β mRNAs and to increase transcript stability in lung adenocarcinomas and lung squamous cell carcinomas when compared to normal controls." (PMID 34829789, 2021).
Lung Injury (1 paper, 2025). "NUDT21 depletion in CX3CR1-expressing cells exacerbates LPS-induced Lung Injury." (PMID 41282183, 2025). "NUDT21 depletion in CD68-expressing cells does not affect LPS-induced Lung Injury." (PMID 41282183, 2025).
malignant glioma (1 paper, 2017). A grade III or grade IV glioma arising from the central nervous system. "Ultimately, NUDT21 was determined as a novel candidate for identifying malignant gliomas." (PMID 29311812, 2017).
melanoma (1 paper, 2023). A malignant, usually aggressive tumor composed of atypical, neoplastic melanocytes. "Fifthly, we identified ‘4‐genes risk prediction model’ (RNF11, NUDT21, RAB31, and ARID4B) and the ‘glycolysis‐prognosis‐10‐gene set’ that each confers independent prognostic significance for melanoma." (PMID 37356089, 2023). "Thirdly, we predicted and validated that Nudt21 affects melanoma metastasis through glycolysis." (PMID 37356089, 2023). "Univariate COX analysis revealed that RAB31, NUDT21, and ARID4B genes were tumor suppressive in clinical melanoma samples (P < 0.1)." (PMID 37356089, 2023).
oral squamous cell carcinoma (1 paper, 2026). "Here, we identify the alternative polyadenylation (APA) regulator NUDT21 as a pivotal therapeutic target in oral squamous cell carcinoma (OSCC)." (PMID 42294590, 2026).
pancreatic adenocarcinoma (1 paper, 2024). "We screened the expression of NDUFS2 in major human cancer species using the TCGA database and GTEx data, and we found that NUDT21 and NDUFS2 were both significantly higher expressed in pancreatic adenocarcinoma (PAAD) compared to control tissues." (PMID 38195952, 2024).
pancreatic cancer (1 paper, 2024). "NUDT21 can be used as a diagnostic and prognostic marker for pancreatic cancer patients in clinic." (PMID 38195952, 2024). "Then, NUDT21 expression in pancreatic cancer was investigated by gene differential analysis and single-gene correlation analysis." (PMID 38195952, 2024). "The effects of NUDT21 on the biological effects of pancreatic cancer cells will be explored by knockdown and overexpression of NUDT21 in pancreatic cancer cell lines." (PMID 38195952, 2024). "To further search for the downstream signaling pathways through which NUDT21 promotes pancreatic cancer cell proliferation and migration by interacting with NDUFS2, we validated the PI3K–AKT pathway postulated by GO and KEGG analysis." (PMID 38195952, 2024). "In conclusion, our results showed that NUDT21 was highly expressed in pancreatic cancer tissues compared with paraneoplastic tissues, and the higher the expression, the worse the prognosis of the patients." (PMID 38195952, 2024). "NUDT21 promotes the proliferation and migration of pancreatic cancer cells through the regulation and stabilization of NDUFS2 and activation of the PI3K–AKT pathway." (PMID 38195952, 2024). "Compared with normal pancreatic tissues, NUDT21 was expressed at a higher level in human pancreatic cancer tissues, which was consistent with the prediction of the bioinformatic results." (PMID 38195952, 2024). "We found that NUDT21 was upregulated in PAAD tissues and was significantly associated with the diagnosis and prognosis of pancreatic cancer through bioinformatic data analysis." (PMID 38195952, 2024). "Overexpression of NUDT21 concordantly promoted both cell proliferation and migration in pancreatic cancer cells." (PMID 38195952, 2024). "CCK8 assay was used to test the function of NUDT21 on the proliferation of pancreatic cancer cell line Panc05.04." (PMID 38195952, 2024). "In addition, we performed GO and KEGG pathway analysis, gene enrichment analysis, and Kaplan–Meier survival analysis to predict the potential function of NUDT21 and its role in the prognosis of pancreatic cancer patients." (PMID 38195952, 2024). "We also filtered all dysregulated genes in pancreatic cancer profiles from TCGA database, and we identified all the upregulated genes and downregulated genes; the Volcano map deciphers the localization of NUDT21 and NDUFS2 in PAAD among all the upregulated genes." (PMID 38195952, 2024). "As a regulator of RNA processing events, we will explore whether NUDT21 could provide a new feasible therapeutic target for the diagnosis and treatment of pancreatic cancer." (PMID 38195952, 2024). "shRNA-mediated depletion of NUDT21 dramatically decreased cell viability, cell colony formation, cell proliferation, cell migration in pancreatic cancer cells as determined by cell apoptosis assay, cell colony formation assay, and cell migration assay, respectively." (PMID 38195952, 2024). "In this study, we will explore the expression of NUDT21 in pancreatic cancer and its effect on patients’ diagnosis and prognosis through preliminary bioinformatic data research, and analyze whether NUDT21 is an oncogene in pancreatic cancer." (PMID 38195952, 2024). "We systematically examined the functional role of NUDT21 in human pancreatic cancer cells." (PMID 38195952, 2024). "Moreover, we found that NUDT21 regulates pancreatic cancer cell proliferation and migration by modulating and stabilizing NDUFS2 and activating the PI3K-AKT signaling pathway through protein mass spectrometry." (PMID 38195952, 2024).
renal fibrosis (1 paper, 2025). A final common manifestation of a wide variety of chronic kidney diseases characterized by glomerulosclerosis and tubulointerstitial fibrosis. "Most recently, we also demonstrated that TRIM65 deficiency alleviates renal fibrosis through NUDT21‐mediated alternative polyadenylation." (PMID 40264575, 2025). "Moreover, the TRIM65 protein plays a role in the regulation of renal fibrosis by targeting the NUDT21‐mediated selective polyadenylation pathway." (PMID 40264575, 2025).
retinoblastoma (1 paper, 2025). A malignant tumor that originates in the nuclear layer of the retina. "A novel siRNA therapeutic targeting NUDT21 (NCT06424301) has been developed for the treatment of retinoblastoma (RB)." (PMID 41153385, 2025).
Rett syndrome (1 paper, 2015). A severe neurodevelopmental disorder affecting the central nervous system.
thymic carcinoma (1 paper, 2024). Thymic carcinoma (TC) is a type of thymic epithelial neoplasm characterized by a high malignant potential. "For aneuploidy, NUDT21 was significantly negatively correlated in thymic carcinoma, KICH, PCPG and OV, while a negative correlation with four cancers (LUSC, ESCA, SARC, HNSC) were positively correlated." (PMID 38349866, 2024).
tumor (36 papers, 2015 to 2026). "We outline a pathogenic mechanism whereby NUDT21 drives this phenotype by forcing a network of tumor suppressor transcripts, notably PTEN, into translationally-repressed, long-3'UTR isoforms." (PMID 42294590, 2026). "The NUDT21 gene, which encodes CFIm25 (a regulator of alternative polyadenylation), can play both tumor suppressor and oncogenic roles depending on the cancer type, yet limited studies have described its m6A-dependent role in cancers." (PMID 38610981, 2024). "Collectively, through dry‐lab analyses, we have pinned the tumor‐suppressor function of Nudt21 to the hallmark of human cancer—deregulated glycolysis." (PMID 37356089, 2023). "NUDT21 is downregulated in BC tumor tissues and its low expression is associated with poor prognosis for BC patients." (PMID 33526057, 2021). "NUDT21, a tumor-associated gene, has been studied for many years, and the protein encoded by this gene, the Cleavage Factor Im (CFIm25), is one subunit of a cleavage factor required for 3′-RNA cleavage and polyadenylation processing." (PMID 29311812, 2017). "NUDT21 is a newly discovered tumor-associated gene according to our current research." (PMID 29311812, 2017). "Truncation of the long 3'UTR of Cdk19 recapitulates cholesterol biosynthesis and proliferative impairments, as well as the enhanced anti-tumor CD8+ T cell activity observed upon NUDT21 depletion, whereas CDK19 overexpression rescues these phenotypes." (PMID 41255211, 2025). "Consistently, immunohistochemistry (IHC) analysis of tumor sections showed elevated FDX1 levels in NUDT21-knockdown xenografts." (PMID 40425546, 2025). "In subcutaneous xenograft models, elesclomol significantly inhibited tumor growth formed by NUDT21-knockdown KYSE30 cells." (PMID 40425546, 2025). "Preclinical studies have shown that NUDT21 inhibition suppresses tumor growth with minimal off-target toxicity." (PMID 41153385, 2025). "Restoration of WT NUDT21 markedly enhanced resistance to elesclomol, while co-treatment with β-alanine reduced tumor volumes and weights, comparable to tumors harboring the NUDT21 K23R mutant." (PMID 40425546, 2025). "To analyze the immune role of NUDT21 in tumor progression, we counted the immunological score of NUDT21 in pan-cancer." (PMID 38349866, 2024). "Taking M2 macrophages as the research object, using different calculation methods on TIMER2.0 to analyze the correlation between the degree of immune infiltration and NUDT21 expression in the whole tumor, and correlations were found in COAD, LUSC and UVM." (PMID 38349866, 2024). "As DMPsi reflects DNA methylation in tumor, we investigated the effect of NUDT21 on epigenetic regulation in cancer." (PMID 38349866, 2024). "Zhu proved that the significant expression of NUDT21 in GC cells promotes tumor cell growth and metastasis by upregulating SGP2 in nude mice." (PMID 38349866, 2024). "In the present study, we suggest that silencing NUDT21 promotes the occurrence of a tumor immune response to HHNSCC, which leads to the development of immunogenic apoptosis." (PMID 38349866, 2024). "The available literature provides evidence supporting the notion that NUDT21 plays a dual role (both oncogenic and tumor suppressor) in the tumorigenesis of different tissues." (PMID 38195952, 2024). "NUDT21 was positively correlated with TMB in 3 tumor types (STAD, LGG, UCEC) and with MSI in tumor types (OV, UCEC, SARC, STAD, CHOL, READ)." (PMID 38349866, 2024). "This analysis was consistent with the tumor‐suppressor attributes of Nudt21 gene that were reported and we characterized above." (PMID 37356089, 2023). "This is achieved via co‐targeting the tumor‐suppressor activity of Nudt21 in OL cells thus synergistically relieving the inhibition of Nudt21 on OL metastasis." (PMID 37356089, 2023).
tumor (continued). "Conversely, NUDT21 silencing stimulated proliferation and clonogenicity of KIRC cells, and this stimulation was relieved following MORC2 silencing, again supporting that NUDT21 acts as a tumor suppressor in KIRC through downregulating MORC2." (PMID 37737260, 2023). "Through dry‐lab analyses, we have pinned the tumor‐suppressor function of Nudt21 to the deregulated glycolysis." (PMID 37356089, 2023). "It characterized NUDT21-regulated genes with shortened 3′-UTRs, and found that ANXA2 and LIMK2 contribute to NUDT21-mediated tumor suppression by augmenting Wnt and NF-κB signaling." (PMID 36816917, 2023). "With the research of tumor, more and more tumor related genes and molecular mechanisms have been gradually explored, such as NUDT21 and APA." (PMID 36816917, 2023). "We found that Nudt21 was negatively correlated with 4 oncogenic genes (blue), and positively correlated with 5 tumor‐suppressive genes (red) in the ‘glycolysis‐prognosis‐10‐gene set’, respectively." (PMID 37356089, 2023). "This is achieved via synergistic co‐targeting of the tumor‐suppressor activity of Nudt21 by secretory ‘S100A11‐Sec23a’ and exosomal miR‐487a‐5p in OL cells." (PMID 37356089, 2023). "Collectively, these results suggest that reduction in NUDT21 is an important component of GBM tumor progression." (PMID 36816917, 2023). "Different studies have reported a dual role of NUDT21 in cancer (both oncogenic and tumor suppressor)." (PMID 36816917, 2023). "In particular, depletion of NUDT21 leads to global 3′ UTR shortening, which has been linked to increased tumorigenesis and tumor development." (PMID 36816917, 2023). "The tumor‐suppressive function of Nudt21 that we predicted and validated is consistent with the literature." (PMID 37356089, 2023). "Meantime, we tested the effect of NUDT21 on tumor metastasis in vivo by nude mice tail vein injection of MKN-28-NUDT21#OE and MKN-28-Vector cells." (PMID 34660260, 2021). "The expression of NUDT21 was positively correlated with tumor size (P=0.017), lymph node metastasis (P=0.020) and clinical stage (P=0.006)." (PMID 34660260, 2021). "In our previous study, we demonstrated that NUDT21 functions as a tumor suppressor in BC and exerts its role via the modulation of alternative polyadenylation." (PMID 34703648, 2021). "For example, NUDT21 was downregulated and functioned as tumor suppressor in glioblastoma, hepatocellular carcinoma, and ovarian cancer." (PMID 34594359, 2021). "In BC tumor tissues, downregulation of NUDT21 promotes the production of ANXA2 and LIMK2 transcripts with longer 3’UTRs, thereby reducing the expression of ANXA2 and LIMK2." (PMID 33526057, 2021). "Based on our previous finding that 3′US represses the ceRNA partners in tumor, we further checked the repression of HK genes in NUDT21 KD." (PMID 32411683, 2020). "Knockdown of NUDT21 further suggested the role of 3′US-ceRNA effect in repressing HK genes for tumor growth." (PMID 32411683, 2020). "Our findings therefore provide insight into the mechanism by which NUDT21 exerts tumor-suppression function in BC." (PMID 31695759, 2019). "This showed expression levels of NUDT21 were negatively correlated with tumor grade (P = 0.014), tumor size (P = 0.024), and clinical stage (T classification) (P = 0.016)." (PMID 31695759, 2019). "However, due to time and cost constraints, this study only conducted cellular functional experiments and has not yet conducted in-depth research on the relationship between NUDT21 and the tumor microenvironment." (PMID 38349866, 2024). "Therefore, in this study, we confirmed that the HNNSCC biomarker NUDT21 promotes tumor development by inhibiting apoptosis." (PMID 38349866, 2024). "Furthermore, our study is based on pan-cancer research and reveals the important contribution of NUDT21 in the immunosuppressive environment of tumor by inhibiting immune stimulation function and immune checkpoint effects." (PMID 38349866, 2024).
tumor (continued). "In addition, immunohistochemistry staining and genetic detection of NUDT21 in HHNCC tumor tissues by immunohistochemistry and qRT-PCR." (PMID 38349866, 2024). "In addition, using HHNSCC as a study target, PCR and pathological detection of NUDT21 in tumor tissues was significantly increased than that in paracancerous normal tissues." (PMID 38349866, 2024). "To confirm the regulatory effect of NUDT21 on the proliferation of FaDu and CNE-2Z tumor cells, we screened if shNUDT21 could effectively silence the expression of NUDT21 (Lv-shNUDT21)." (PMID 38349866, 2024). "Therefore, we plan to further investigate the role of NUDT21 in the immune regulation of HHNSCC in the tumor microenvironment." (PMID 38349866, 2024). "Moreover, NUDT21 was shown to function as a tumor suppressor in KIRC mainly dependent on MORC2 downregulation." (PMID 37737260, 2023). "Finally, we designed an antisense oligonucleotide (ASO) to enhance NUDT21 expression and validated that it was effective in repressing proliferation and tumor formation of KIRC cells." (PMID 37737260, 2023). "The global 3’UTR shortening landscape and 3’UTR shortening of specific genes could have opposite effect thus when we discuss about the impact of Nudt21 on tumor growth it should be evaluated on a case by case basis." (PMID 36816917, 2023). "ASO, which enhances NUDT21 expression, inhibits proliferation and tumor formation of KIRC cells." (PMID 37737260, 2023). "NUDT21 functions as a tumor suppressor in KIRC, mainly depending on MORC2 downregulation." (PMID 37737260, 2023). "Additionally, NUDT21 was confirmed to act as a tumor suppressor mainly depending on downregulation of MORC2." (PMID 37737260, 2023). "In our previous report, we identified NUDT21 as a tumor suppressor in BC progression." (PMID 34703648, 2021). "NUDT21 but also promoted tumor growth and metastasis in nude mice." (PMID 34660260, 2021). "As a crucial regulator of APA, NUDT21 has been reported to be a tumor suppressor in human cancers." (PMID 33526057, 2021). "Since they are much less than the other HK genes in number (e. g., 705 3′US ceRNA HK genes vs. HK genes in the NUDT21 KD experiment), our definition may shed novel insights into identifying another set of biomarkers indicating tumor progression." (PMID 32411683, 2020). "Currently, whether persistent MES identity or MES phenotype shift influenced by NUDT21 could promote tumor growth is unknown that warrant more research regarding molecular and phenotypic characterization of these tumors." (PMID 29311812, 2017). "Then we exerted RT-qPCR analysis, to examine the NUDT21 expression level in tumor tissues." (PMID 29311812, 2017). "Next, we examined whether NUDT21 was expressed by TISIDB in different tumor immune subtypes." (PMID 38349866, 2024). "Currently, the mechanism of NUDT21 in tumor development remains unclear." (PMID 38349866, 2024). "Additionally, NUDT21 expression displayed a negative association with tumor grade and a positive association with KIRC prognosis." (PMID 37737260, 2023). "Therefore, Bcl-2 and CCNE1 might contribute to the tumor promoting role of the NUDT21/SGPP2 pathway." (PMID 34660260, 2021). "This siRNA selectively silences NUDT21, a regulator of 3′UTR processing that promotes tumor proliferation through SMC1A stabilization." (PMID 41153385, 2025). "Not surprisingly, the 12 cancers with positive correlation between tumor stemness and NUDT21 also showed consistent HRR characteristics, suggesting that NUDT21 interacts with cancer stemness through DNA repair." (PMID 38349866, 2024). "NUDT21 posttranscriptional regulation of APA plays a key role in gene reprogramming, stem cell directed differentiation and tumor progression." (PMID 36816917, 2023). "In HCC, the CPA complex, NUDT21 (also known as CPSF5 or CFIm25), has been reported to be a tumor suppressor that inhibits tumor growth and metastasis by regulating APA." (PMID 33748106, 2021).